IGF1R (insulin like growth factor 1 receptor)
Diseases named in the same sentence as IGF1R in open-access papers (continued):
Sharing a sentence is not in itself a finding about the gene and the disease.
breast cancer (continued). "In this study, we investigated the promotive effects of lncRNA NR2F1‐AS1 on breast cancer angiogenesis both in vitro and in vivo, declaring the potential mechanism through inducing the expression of IGF‐1 in breast cancer cells and then activating IGF‐1R/ERK pathway in endothelial cells." (PMID 32548873, 2020). "Interestingly, overexpression of FGFR3 and IGF1R in breast cancer (more specifically in MCF-7 for FGFR3) has been observed in previous studies, each related to breast cancer expansion through stem cells." (PMID 30566622, 2019). "The expression of IGF1R, a 95‐kDa transmembrane tyrosine kinase receptor, was initially investigated in MDA‐MB‐231, MDA‐MB‐453, MCF7, and BT474 cell lines that correspond to the basal, HER2‐positive, luminal A, and luminal B breast cancer subtypes, respectively." (PMID 28766847, 2018). "To test whether attenuated IGF-1R function in human breast tumor cells directly alters the recruitment of monocytes, we modeled migration in vitro with the xCELLigence RTCA DP real-time migration assay using the MCF7 breast cancer cell line." (PMID 30458886, 2018). "This might indicate that in women with tumors not expressing hormone receptors, the IGF1R signaling pathway might be an alternative way of breast cancer development, since this type of tumor is not dependent on the common ER/PR-signaling." (PMID 29486734, 2018). "Moreover, patients with early breast cancer harbored IGF1R(+) CTCs more commonly than metastatic patients, whereas none of them presented exclusively IGF1R(−) CTCs compared to 21% of metastatic patients." (PMID 28766847, 2018). "This study may provide a better understanding of IGF1R-signaling and help to explain the lack of clinical outcome benefit of IGF1R-directed monotherapies in breast cancer." (PMID 29207959, 2017). "Based on the qPCR results in the RPPH1 function cell models, we may infer that RPPH1 promoted breast cancer cell proliferation and cell cycle progression through down-regulation of micro-RNA 122 and influence the expression of ADAM10, PKM2, NOD2 and IGF1R genes." (PMID 29200969, 2017). "As IRS-1 and IRS-2 are thought to mediate most of the effects of IR and IGF-1R in breast cancer cells, it may be possible to disrupt this molecule without affecting normal glucose homeostasis mediated by other adapter proteins in insulin target organs." (PMID 29152592, 2017). "We anticipate that this study may constitute the starting point for future attempts to clinically circumvent the negative effects of IGF1R overstimulation in breast cancer patients." (PMID 27179633, 2016). "Collectively, our studies demonstrate that erbB3 receptor and IGF-1R differentially modulate lapatinib sensitivity in trastuzumab-resistant breast cancer cells; and specific knockdown of erbB3, but not IGF-1R, significantly promotes lapatinib-mediated growth inhibition and apoptosis." (PMID 26621843, 2016). "For over a century, a lot of efforts were invested in developing strategies to target IGF1 receptor (IGF1R) in cancer therapy, but accumulating data from clinical study indicated that specific targeting of the IGF1R was not efficient as an anti‐breast cancer therapy." (PMID 26923183, 2016). "IGF1R expression does not affect breast cancer specific survival in luminal A tumors." (PMID 25964777, 2015). "The majority of breast cancer specimens expressed HRs rather than IGF-1R." (PMID 26217584, 2015). "Upon ligand binding, IGF-1R becomes auto-phosphorylated and subsequently recruits specific docking intermediates, including insulin-receptor substrate-2 (IRS-2), that activate PI3K/AKT and Ras/Raf/MAPK pathways in order to promote cell motility and pro-metastatic behaviour in breast cancer cells." (PMID 25629807, 2015).
breast cancer (continued). "High expression of insulin-like growth factor 1 receptor (IGF1R) and its two ligands, insulin-like growth factor 1 (IGF1) and insulin-like growth factor 2 (IGF2) have been demonstrated in OS, as well as many other cancers including rhabdomyosarcoma, breast cancer, prostate cancer, and colon cancer." (PMID 25170759, 2014). "We previously reported that the three RTKs, erbB2, erbB3, and IGF-1R interacted with each other to form a heterotrimeric complex, which activates the downstream signaling, such as PI-3 K/Akt or MEK/MAPK pathways and Src kinase in trastuzumab-resistant breast cancer cells." (PMID 24168763, 2013). "Therefore a panel composed of IGF-1R, CD44v6, GLUT1, CAXII, FGFR2, and EGFR might be suitable for molecular imaging of male breast cancer." (PMID 23308200, 2013). "In search of the minimal panel of targeted probes needed for the highest possible detection rate, we showed that 80% of all breast cancers express at least one of a panel of membrane markers (CD44v6, GLUT1, EGFR, HER2, and IGF1-R) that may therefore be suitable for molecular imaging strategies." (PMID 22695343, 2012). "Insulin-like growth factor 1 receptor (IGF-1R), which shares approximately 60% homology with IR, is a transmembrane tyrosine kinase activated by the binding of its ligand (IGF-1) and promotes mitogenic, metastatic, and anti-apoptotic phenotypes in breast cancer." (PMID 22203527, 2011). "There is little evidence of gene amplification of IGF1R in breast cancer, and the level of IGF1R could vary from the primary tumour to metastatic tumours." (PMID 19491901, 2009). "Although we have presented prior evidence that high IGFBP7 expression by breast cancer tissue or high circulating levels of this protein are related to poor prognosis, this protein has not previously been studied in relation to the efficacy of IGF-1R targeted therapies." (PMID 39362991, 2024). "High levels of IGF-1R are seen on the membrane and/or the cytoplasm, and in the nucleus of numerous cancer cell types including prostate cancer, head and neck squamous cell cancer, breast cancer, pancreatic cancer, colorectal cancer, non-small cell lung cancer, Ewing sarcoma, and osteosarcoma." (PMID 37858153, 2023). "In addition, MUC1 and IGF1R co-expressed with CTD-2566J3.1 had AUC > 0.6 and were found significantly over-expressed in patients without response to therapy, indicating that down-regulation of these mRNAs can modestly discriminate PCR in patients with luminal B breast cancer." (PMID 36359853, 2022). "Even though our findings require validation in an independent cohort of ER+, IGF‐1R‐positive breast cancer patients on adjuvant tamoxifen, our data suggest that IGF‐1R/InsR inhibition might be an overlooked treatment option for patients with tumors harboring an activated IGF‐1R signaling route." (PMID 31490549, 2020). "In this study, we find that the Insulin/IGF1R signaling pathway is activated in 78 of 90 (~ 87%) of patients with invasive breast cancer and in 45 of 51 (~ 88.2%) TNBC patients, suggesting IGF may be a promising therapeutic target for this highly aggressive breast cancer subtype." (PMID 29367764, 2018). "Nonetheless, our findings indicate that GPER and the IGF1/IGF1R axis are co-expressed in human breast tumors, suggesting that targeting IGF1R/GPER cross-talk might be useful in halting the angiogenesis process, particularly in a subset of breast cancer patients devoid of the classic ER." (PMID 29212519, 2017). "However, it remains unclear whether erbB3- and IGF-1R-initiated signaling pathways possess distinct effects on the sensitivity of lapatinib, a dual tyrosine kinase inhibitor against both EGFR and erbB2, in trastuzumab-resistant breast cancer." (PMID 26621843, 2016). "Hence, for breast cancer, INSR/HR:IGF-1R ratio may predict response to mAb against IGF-1R." (PMID 26217584, 2015).
breast cancer (continued). "IGF1R mRNA was found not to be significantly altered following miR-630 manipulation; thus we propose that the predominant mechanism of action for miR-630 in breast cancer cells is likely to be at a post-transcriptional level by its inhibition of IGF1R protein translation." (PMID 24655723, 2014). "Based on our current findings, we propose that obesity-induced systemic factors promote breast cancer progression and may increase resistance to aromatase inhibitor therapy by initiating crosstalk between nongenomic ERα activity and the IGF-1R, PI3K/Akt and MAPK signaling pathways." (PMID 23880059, 2013). "In breast cancer, the role of miR-126 in tumor metastasis may be related to the negative regulation of insulin receptor substrate-1 expression and it inhibits endothelial cell recruitment and angiogenesis through the negative regulation of IGFBP2/IGF1/IGF1R and GAS6/ MERTK signaling pathways." (PMID 24350576, 2013). "Therefore, we emphasize that IGF-1R signaling may act as a crucial contributor to antiestrogen resistance in breast cancer, independently of E2 and regardless of ER status." (PMID 21595894, 2011). "Studies have found that IGF2/IGF-1R/IRS1 signal pathway is normally inhibited through negative feedback to maintain basic cell survival and proliferation in HER2-positive human breast cancer cells." (PMID 34837929, 2021). "In the ER+ breast cancer cell lines, a specific antibody against IGF‐1R was not able to block downstream PI3K/MAPK signaling or tumor cell proliferation, unlike the dual IGF‐1R/InsR inhibitor linsitinib." (PMID 31490549, 2020). "In oestrogen receptor-α negative (ERα-) and positive (ERα+) breast cancers, the activation of CB2R by JWH-015 reduced breast cancer cell survival via blocking of the EGFR and insulin-like growth factor-1 receptor (IGF1R) pathways." (PMID 32340151, 2020). "With the exception of two neoadjuvantly treated mammary carcinomas, PLA showed moderate to strong Rad18/PCNA colocalization signals in all cases (including some IGF1R/PCNA negative cases)." (PMID 32701997, 2020). "Using both immunofluorescence and cell fractionation techniques we identified the IGF1R in the nucleus of both non-carcinogenic MCF10A and carcinogenic MCF7 human breast cancer cell lines." (PMID 28945762, 2017). "The MCF7 breast cancer line had a high level of IGFR1 expression while the K562 erythroleukemia and Daudi lymphoma lines had a low or no expression of IGF1R, respectively." (PMID 26173023, 2015). "In particular, in ER depleted C4.12.5 breast-cancer cells but not in ER-positive MCF-7 cells, IGF-1R and IR were able to bind to the promoter of IGF-1R after translocation into the nucleus." (PMID 25798130, 2015). "Across all cases, overall survival and breast cancer-specific survival, unadjusted for confounders, did not vary by expression of IGF1, IGF1R, IGFBP2, or IGFBP3." (PMID 25619494, 2015). "Expression of IGF1-R, MET, FGFR2, and CD44v6 was not correlated to clinicopathological features in both male and female breast cancer." (PMID 23308200, 2013). "Neither expression of IGF1R nor IR had any significant correlation with distant disease free survival (DDFS), disease free survival (DFS) or overall survival (OS) in a cohort of basal-like breast cancers." (PMID 36920947, 2023). "Indeed, crosstalk occurred between IGF-1R and HER2, and IGF-1R physically interacted with HER2 and induced HER2 activation in Herceptin-resistant, but not -sensitive breast cancer cells." (PMID 33976188, 2021). "Indeed, in ERα‐positive breast cancer cell lines, IGF‐1R activation rather than IGF‐1R (over)expression stimulated downstream MAPK/PI3K signaling cascades, resulting in cell proliferation despite tamoxifen exposure." (PMID 31490549, 2020).
lung cancer (230 papers, 2008 to 2026). A malignant neoplasm involving the lung. "The IGF-1R is a cell surface receptor involved in cell growth and proliferation, and overexpression is associated with lung cancer, as it can stimulate the growth and survival of cancer cells." (PMID 38905286, 2024). "Given that tobacco smoking is the main risk factor for lung cancer, several studies have shown that tobacco smoke-specific carcinogens activate IGF-1R signaling pathways." (PMID 38540176, 2024). "Tobacco smoking also leads to disruptions in the renin-angiotensin system, which has been implicated in lung cancers and has been shown to mediate the activation of the IGF-1R signaling axis." (PMID 38540176, 2024). "Among these genes, epidermal growth factor receptor (EGFR) and insulin-like growth factor 1 receptor (IGF1R), which have been shown to be associated with lung cancer metastasis and progression, were selected for further studies." (PMID 37880793, 2023). "The clinical data revealed that the expression of EGFR and IGF1R is associated with poor outcomes in lung cancer patients." (PMID 37880793, 2023). "In lung cancer patients, high IGF1R expression was associated with reduced survival outcomes and increased postoperative recurrence." (PMID 36224313, 2022). "IGF-1R is implicated, and often overexpressed, in a variety of human cancers, including lung cancer." (PMID 36361620, 2022). "Here, reduced mRNA expression levels of IGF1R were associated with a significantly better OS in lung cancer patients compared to patients with high IGF1R mRNA expression levels." (PMID 35574343, 2022). "On the other hand, we demonstrated that in AXL-low-expressing EGFR-mutated lung cancer cells, osimertinib exposure increased protein expression and phosphorylation of IGF-1R and thereby restored the survival signal mainly via Gab1 and IRS1 to emerge tolerant." (PMID 32929081, 2020). "The insulin-like growth factor 1 receptor (IGF-1R) is a membrane receptor tyrosine kinase that is implicated in several cancers, including prostate, breast, and lung cancers." (PMID 32340152, 2020). "It is known that Kirsten rat sarcoma viral oncogene homolog (KRAS) mutation is one of the most common genetic alterations involved in lung cancer and is associated with reduced response to IGF1R-targeted therapy in lung cancer cells." (PMID 29455661, 2018). "We further reveal the association between polymorphisms of IGF1R gene and different clinical N stage of lung cancer in different types of patients." (PMID 27213344, 2016). "Taken together, our results provided direct evidence that activation of IGF1R is one of the mechanisms underlying acquired drug resistance to EGFR-TKIs in lung cancer cells." (PMID 26554308, 2015). "It has recently been reported that in lung cancer IGF1R endocytosis is triggered by ligand binding, causing IGF1R ubiquitination and internalization via clathrin-coated vesicles and/or caveolae." (PMID 21611203, 2011). "Our results indicate that optimal inhibition of the tolerant signal via IGF-1R combined with osimertinib may dramatically improve the outcome of AXL-low-expressing EGFR-mutated lung cancer." (PMID 32929081, 2020). "With regard to whether circ‐IGF1R is associated with the clinical characteristics of lung cancer, the analysis showed that the abnormal expression of circ‐IGF1R was associated with the T stage (P = 0.0272) and the N stage (P = 0.0159)." (PMID 32107851, 2020). "However, fewer studies were reported for association between IGF1R gene polymorphisms and lung cancer." (PMID 27213344, 2016). "Furthermore, hypoxia increases the population of lung cancer stem cell resistant to gefitinib in EGFR mutation-positive NSCLC by activating IGF1R." (PMID 27463019, 2016). "In addition, although the A549 lung cancer cell line is partially sensitive to gefitinib, chronic exposure resulted in a resistant variant with increased activity of elements of the IGF-1R pathway." (PMID 22545054, 2012).
lung cancer (continued). "Thus, we investigated whether the PRKCSH-mediated extension of the IGF1R half-life is linked to IRE1α activation in lung cancer." (PMID 38200153, 2024). "Since IGF1R has been implicated in the pathogenesis of lung cancer by facilitating metastasis, tumor-associated inflammation and immune checkpoint regulation, we decided to assess whether IGF1R deficiency in the TME delays implantation and progression in a heterotopic LLC mouse model." (PMID 35688943, 2022). "The present study found that circ‐IGF1R is downregulated in lung cancer, and its expression level is associated with larger tumors and lymph node metastasis, suggesting that circ‐IGF1R may indicate the poor prognosis of patients with lung cancer." (PMID 32107851, 2020). "Moreover, transient inhibition of IGF-1R with osimertinib could lead to the eradication of EGFR-mutated lung cancer cells." (PMID 32929081, 2020). "Findings from previous studies in lung cancer suggest that IGF1R confers immunotherapy resistance by sustaining tumor immunosuppression." (PMID 40227722, 2025). "In lung cancer, lactylation of the insulin-like growth factor 1 receptor (IGF1R) increases its stability and downstream signaling, thereby enhancing lactate generation and sustaining oncogenic metabolism." (PMID 40843350, 2025). "BMS-754807, with dual IGF-1R/InsR tyrosine kinase inhibition, has promising anti-tumor activity against various cancers, including breast, pancreatic, and lung cancers." (PMID 39773329, 2025). "Quiescent lung cancer cells release exosomes that are internalized by BMSCs, enhancing the glycolytic capacity of BMSCs via the insulin-like growth factor 1 receptor (IGF-1R) signaling pathway." (PMID 40028322, 2025). "Blocking IGF-1R signaling or glycolytic pathways effectively slows the proliferation of lung cancer cells within the bone marrow." (PMID 40028322, 2025). "Various studies have shown that tobacco smoke carcinogens can activate growth factor receptors, including IGF-1R, which play an important role in lung cancer development." (PMID 38540176, 2024). "recently showed that PRKCSH increased the stability and activation of the insulin-like growth factor 1 receptor (IGF1R) in lung cancer." (PMID 38571496, 2024). "In this review, the significant role of the IGF/IGF-1R signaling axis in the development and progression of lung cancer, particularly in the context of tobacco smoke-induced carcinogenesis, is highlighted." (PMID 38540176, 2024). "Gaining further clarity on the pivotal role of IGF-1R in lung cancer development is instrumental in identifying effective treatment strategies for this malignant disease." (PMID 38540176, 2024). "The activation of IGF-1R by carcinogens in tobacco smoke can have significant downstream effects on lung cancer development, promoting cell growth, proliferation, and survival." (PMID 38540176, 2024). "Monoclonal antibodies that target IGF-1R, such as cixutumumab, dalotuzumab, and figitumumab, are used for both in vitro and in vivo lung cancer treatments." (PMID 38540176, 2024). "In lung cancer targeting, the KRAS G12C mutation has been shown to have add-on effects/synergy with other treatments such as mTOR and IGF1R inhibitors in vitro and in vivo." (PMID 38607041, 2024). "The gain of IGF1R in PRKCSH-deficient cells increased caspase-8 phosphorylation and Mcl-1 expression levels, whereas IGF1R knockdown reduced caspase-8 phosphorylation and Mcl-1 expression levels in lung cancer cells." (PMID 38200153, 2024). "Here, we demonstrate that protein kinase C substrate 80K-H (PRKCSH) abundance in lung cancers boosts oncogenic IGF1R activation, leading to TNFSF resistance." (PMID 38200153, 2024). "Because of this, the IGF-1R signaling pathway serves as an attractive target for the development of lung cancer treatments." (PMID 38540176, 2024).